EPO (erythropoietin)
Diseases named in the same sentence as EPO in open-access papers (continued):
Sharing a sentence is not in itself a finding about the gene and the disease.
cancer (continued). "In contrast, some cancer cell lines have been reported to be non-responsive to EPO, although they express EPOR transcripts, but not functional EPOR." (PMID 36052260, 2022). "The factors responsible for cancer cell proliferation may be a higher level of pro-inflammatory cytokines (TNF-α and CXCL8) and growth factors (VEGF, HCF, Ang-2, TGF-α, EPO, SCF, FGF, and PDGF-BB)." (PMID 34577154, 2021). "Moreover, we found two key TFs (EPO, ARID3A), four key PRSGs (CACNA1E, LINC01356, CGA and SSX3) and five key hallmarks of cancer gene sets (DNA repair, myc targets, E2F targets, mTORC1 signaling and unfolded protein response) in the regulatory network." (PMID 33816287, 2021). "Facility‐based hemodialysis patients with recent cancer treatment, however, receive a higher dose of erythropoietin‐stimulating agent than those without cancer." (PMID 30623084, 2018). "High mRNA and protein levels of EPO and EPOR have been reported in several cancer cell lines." (PMID 28430808, 2017). "Since EPO is a survival factor in erythroid progenitor cells, we investigated whether EPOR knockdown in cancer cell lines would lead to apoptosis." (PMID 28418910, 2017). "For instance, miR-125b downregulates EPO and EPOR expression in breast MCF7 cancer cell lines." (PMID 25324845, 2014). "Clinical studies exploring prognostic significance of EPO and EPOR expression in cancer patients." (PMID 25426117, 2014). "Erythropoietin (EPO) was first considered to have a single biological purpose and action – the stimulation of RBC growth and differentiation and, as such safe, for use in cancer patients." (PMID 25426117, 2014). "EPO and its receptor, EPOR, are expressed in many cancers, including RCC." (PMID 23305401, 2013). "EPO may also stimulate epithelial-mesenchymal transition (EMT) in RCC, and pathological EMT has a key role in cancer progression." (PMID 23305401, 2013). "Now, we know that EPO-EPOR signaling is active in a variety of solid tumors, that EPO-EPOR expression is particularly increased in hypoxic regions and can influence cancer resistance to pharmacological treatments." (PMID 24165569, 2013). "The synergistic effect of EPO and SCF on EPO production observed under normoxic condition in Mz-Cha-2 cells, with a concomitant increase of EPO gene expression, PCNA and CyclinD1, indicates a sensitization to EPO responsiveness as already observed in another cancer cell line." (PMID 23052842, 2013). "In addition, high levels of EPO and EPO receptor (EPOR) were found in various cancer cell types and the EPO/EPOR system was known to induce proliferation, angiogenesis and even inhibit apoptosis." (PMID 23825635, 2013). "If that is the case, EPO is more likely to be a local player in cancer progression, rather than contributor of metastatic progression." (PMID 23305401, 2013). "In addition, EPO may affect immune cell differentiation and proliferation and it will be of importance to determine such immune-regulatory effects in regard to T cell differentiation or macrophage polarization (M1 versus M2 phenotype) under inflammatory conditions and in cancer models in vivo." (PMID 22094132, 2012). "Erythropoietin (EPO) and its cell surface receptor (EPOR) are essential for erythropoiesis; can modulate non-erythroid target tissues; and have been reported to affect the progression of certain cancers." (PMID 22253704, 2012). "Under hypoxic condition HIF-1 coordinates the expression of many genes that orchestrate angiogenesis and cancer cell metabolism reprogramming, including GLUT1 and GLUT3, glycolytic enzymes, vascular endothelial growth factor (VEGF), erythropoietin (EPO), heme oxygenase-1 (HO-1), etc." (PMID 23144690, 2012). "One of the surprising newly recognized consequences of EPO therapy in humans that has emerged over the past several years has been the unexpected negative effect of EPO therapy on survival in cancer patients." (PMID 18382691, 2008).
cancer (continued). "Although local erythropoietin blockade in tumors may represent one approach to overcome this problem, selective inhibition of EPOR function to specifically target cancer cells may constitute an alternative future strategy." (PMID 17579721, 2007). "The guideline focused on the role of erythropoietin (EPO) in the management of cancer patients with non-hematologic malignancies." (PMID 15715916, 2005). "However, the anti-apoptotic and proliferative effects of EPO are not cell type-specific, and evidence indicates that EPO can directly enhance the proliferation of cancer cells." (PMID 41602576, 2026). "However, the great number of patients being treated with EPO enabled the assessment of its negative side effects (increased risks of cardiovascular diseases and acceleration of cancer progression)." (PMID 38672425, 2024). "The controversy over the biological activity of EPO in cancer cells and the supposed non-specificity of the M-20 and C-20 antibodies led to a long debate about whether cancer cells express the receptor for EPO." (PMID 38672425, 2024). "Cytokines used in cancer immunotherapy can be divided into the following categories: 1 IL-2 Family: IL-2,7,15,21; 2 IFN-α; 3 IFN-γ; 4 IL-12; 5 TNF; 6 colony-stimulating factor (CSF) Family: GM-CSF, Granulocyte (G)-CSF, erythropoietin (EPO), IL-3; 7 IL-1 Family: IL-1,18." (PMID 36559100, 2022). "Since there is no clear and conclusive evident association between the worsening prognosis and transfusion only, the high-dose recombinant human erythropoietin and iron supplementation in cancer patients still should be preserved to those without other alternative choices." (PMID 34436045, 2021). "Nonetheless, the negative impact of EPO in cancer patients is controversial or not straightforward." (PMID 29137269, 2017). "Those without cytogenetic abnormalities and endogenous erythropoietin levels < 500 ng/ml are more likely to respond, but response may take longer than in other cancers." (PMID 26373748, 2015). "In cancer patients, EPO treatment to increase hemoglobin levels approaching the normal range resulted in increased adverse events including venous thromboembolism and cancer progression, particularly in select solid cancers such as metastatic breast cancer and head and neck cancer." (PMID 22567318, 2012). "Finally, support treatment with antiemetic drugs, erythropoietin stimulating agents, granulocyte-colony stimulating factor (G-CSF), and bone resorption inhibitors has involved a cost of EUR 5,751,910, which represents 4.6% of the overall pharmacological cost of cancer treatment." (PMID 37754495, 2023). "Furthermore, some cancer cells may exhibit constitutive activation of EPOR pathways, suggesting that observed effects of signal transduction through the EPOR in these cells are EPO-independent." (PMID 35694408, 2022). "Indeed, EPO antagonized trastuzumab-induced therapeutic effects through JAK2-mediated activation of SRC and inactivation of PTEN protein, so combined therapy of HER2-positive cancer cells with EPO and trastuzumab reduced the response of these cells to trastuzumab both in vitro and in vivo." (PMID 25426117, 2014). "We suggest that the concurrent use of long-termed EPO/ESA and anti-cancer treatment is the main reason for EPO/ESA negative effects on response to anti-cancer therapy, overall survival, and disease recurrence." (PMID 25426117, 2014).
infection (106 papers, 2006 to 2026). The state of being infected such as from the introduction of a foreign agent such as serum, vaccine, antigenic substance or organism. "Western blotting results showed that the levels of EPO protein in SZ rats were significantly reduced, while adeno‐associated virus 9(AAV9)/EPO infection increased the levels of EPO protein to a normal level." (PMID 39467064, 2024). "The total infection incidence was associated with age, the presence of obstructive kidney disease, and the need for higher erythropoietin dosages." (PMID 34268290, 2021). "Other disease-related factors with potential to increase thrombotic risk include use of central venous catheters (CVC), erythropoietin-stimulating agents (ESAs), hospitalization, and infection." (PMID 27999418, 2016). "The data presented here suggest that anti-EPO Ab is produced at infection and is associated with Hb loss." (PMID 23978045, 2013). "Therefore, the upregulation of Marco and Cnlp by EPO-mediated re-programming of endotoxin-tolerant macrophages would be particularly helpful for septic patients who are at high risk of secondary infections." (PMID 36016936, 2022). "Thus, our findings of improved PROs, infection rates, and lower erythropoietin and iron requirements are congruent with the underlying physiological effects of the MCO membrane." (PMID 35083060, 2022). "During the eosinophil-dependent protective response in primary in vivo infection with either B. malayi Mf or S. stercoralis L3, EPO is released into the bloodstream and deficiency of EPO or MBP-1 can enhance the establishment of L. sigmodontis L3 in non-permissive mouse strains." (PMID 24626328, 2014). "With blood pressure and volume control, discontinuation of erythropoietin, and treatment of a presumed underlying infection in the first presentation, the patient’s seizures and visual symptoms abated and follow-up imaging normalized one month after each instance of PRES." (PMID 24411012, 2014). "As upregulation of hepcidin by inflammation and iron status was blunted by erythropoietin in this population, enhanced iron absorption through the low hepcidin values may increase infection risk." (PMID 24339866, 2013). "The infection caused clinical CM, which was counteracted by EPO." (PMID 22741599, 2012). "The down-regulation of EPOR by pro-inflammatory stimuli may result from a feedback mechanism in order to limit the anti-inflammatory effects of EPO under conditions in which these are associated with poor outcome such as in infections." (PMID 22094132, 2012). "The influence of EPO on systemic iron homeostasis and hepcidin expression is of major interest in infection, because the availability of iron for pathogens is a hallmark deciding on the fate of many infections." (PMID 22094132, 2012). "The early postinfectious phase is characterized by a decreased reticulocyte concentration and delayed EPO production, followed by a marked reticulocyte expansion 1–3 months after the infection." (PMID 40126283, 2025). "This relationship manifests as an initial increase in the erythropoietin resistance index (ERI) following infection, with a delayed recovery phase observed months after diagnosis." (PMID 40126283, 2025). "NLR is more recognized in predicting EPO resistance, rapid progression of renal function, and infection-related complications." (PMID 39950124, 2025). "Herein, in our infection study, we noticed a significant increase in erythropoietin (EPO) levels in P. yoelii infected mice, along with downregulation of hepatic hepcidin expression and a marked upregulation of Fpn expression." (PMID 40871363, 2025). "Reinfected mice performed better as a higher concentration of EPO was measured in blood despite reduced RBC counts in the first phase of the infection." (PMID 38892340, 2024). "Important factors related to hepcidin and systemic iron homeostasis include plasma iron concentration, body iron storage, infection, inflammation, and erythropoietin." (PMID 36930080, 2023).
infection (continued). "FPS-ZM1 treatment also reduced levels of MMP-9 on day 2 after infection and EPO on day 4 after infection." (PMID 35076028, 2022). "In previous studies, we found that EPO promoted infection resolution and ameliorated inflammatory response through a ligand-activated transcriptional factor peroxisome proliferator–activated receptor gamma (PPAR-γ) in macrophages." (PMID 36016936, 2022). "In accordance with these studies, our data showed an upregulation of Marco and Cnlp gene expression by EPO and we observed an enhanced ability in bacterial clearance by EPO pretreatment in LPS-tolerized mice subjected to secondary infection of E. coli." (PMID 36016936, 2022). "Studies have illustrated that EPO can induce the expansion of highly proliferative early-stage CECs (CD45+ CECs), and neutralization of EPO prevents infection-related CEC accumulation." (PMID 35251018, 2022). "Together these results suggest that EPO promotes Gram-positive S. aureus phagocytosis and enhances vancomycin anti-bacterial actions in S. aureus-initiated infections." (PMID 33927725, 2021). "Collectively, these results indicate that EPO promotes bacterial clearance and improves ciprofloxacin actions in the delayed resolution of E. coli-initiated infections." (PMID 33927725, 2021). "The present data show that EPO directly modulates host innate immunity enhancing phagocytosis, eliminating microbes, and thus accelerating resolution of infections." (PMID 33927725, 2021). "Thereafter, we determined the effect of EPO and vancomycin on S. aureus-initiated infections in murine dorsal skin pouches." (PMID 33927725, 2021). "Specifically, upregulation of MAPK TREM1 and IL17 signalling pathways and downregulation of erythropoietin and cholesterol biosynthesis pathways were observed after infection with MA08." (PMID 34671358, 2021). "Herein, we found that EPO promoted infection resolution and lowed the antibiotic requirements of Escherichia coli (E. coli)- and Staphylococcus aureus (S. aureus)-initiated infections." (PMID 33927725, 2021). "EPO is anti-phlogistic, increases engulfment, promotes infection resolution, and lowers antibiotic requirements." (PMID 33927725, 2021). "Together with previous observations our results suggest that EPO is an endogenous pro-resolving molecule essential for infection resolution." (PMID 33927725, 2021). "Here our results demonstrate that EPO is temporally induced during infections and EPO is anti-phlogistic, increases engulfment, promotes infection resolution, and enhances antibiotic action in E. coli- and S. aureus-initiated infections." (PMID 33927725, 2021). "Collectively, these data demonstrate that macrophage EPO signaling is essential for infection resolution and exogenous EPO promotes acute infection resolution." (PMID 33927725, 2021). "Collectively, these results suggest that a correlation exists between macrophage EPO signaling activation and infection resolution." (PMID 33927725, 2021). "To further explore the link of the reduction in DDC, dACE2 and EPO expression with virus-induced cell death, we comparatively employed the infection models of DENV and HCV at late hours post-infection." (PMID 34185793, 2021). "Here we described for the first time that EPO enhanced bacterial phagocytosis and killing by macrophages which promoted infection resolution." (PMID 33927725, 2021). "These included: metabolic acidosis, ongoing infection, higher doses of erythropoietin and higher serum concentrations of ionized calcium and phosphate." (PMID 33804005, 2021). "Myeloid-specific EPOR-deficient mice exhibited an impaired inflammatory resolution and exogenous EPO enhanced this resolution in self-limited infections." (PMID 33927725, 2021). "The rate of post-operative infection and length of hospitalization were significantly decreased in patients who received EPO intervention." (PMID 32993140, 2020).
infection (continued). "Hypoxia-inducible factor-1 (HIF-1) is a transcription factor that control hypoxia-activating genes, such as erythropoietin (EPO), and can be positively linked with pathogen infection." (PMID 32635653, 2020). "Supportive management like appropriate infection control, fresh frozen plasma and red cell concentrate transfusions, injection transaminase and erythropoietin are often life-saving in such cases." (PMID 31355064, 2019). "Although significant enhancement of EPO expression was detected in the kidney of wild type mice with infection, number of reticulocytes was significantly decreased, suggesting a possible impairment of EPO biological activity." (PMID 30586912, 2018). "In the presence of safer and more potent alternatives like intravitreal EPO injection, risky surgeries should be avoided to prevent serious complications like ophthalmic or carotid artery injury, CSF leak, and infection." (PMID 30647957, 2018). "Upon infection, the mRNA expression of EPO in the kidney was significantly increased in both α-TTP knockout and wild type mice compared to the pre-infection levels." (PMID 30586912, 2018). "Strikingly, the VP1u receptor appeared to be expressed only on erythropoietin-dependent erythroid differentiation stages that also provide the necessary intracellular factors for a productive infection." (PMID 27690083, 2016). "EPO (which is elevated during infection with Salmonella) was shown to increase the numbers of splenic macrophages, upregulate the expression of F4/80, CD11b, and CD80 cell markers, and enhance their pro-inflammatory and phagocytic activity." (PMID 26068006, 2015). "In EPO−/− mice there was also a reduction in nematode-infection induced lung hyper-responsiveness and in the baseline respiratory rate, suggesting that release of EPO plays a role in nematode-induced lung pathology." (PMID 24626328, 2014). "EPO−/− and wild-type mice were infected with B. malayi Mf alone (primary infection) or following immunisation with Mf antigen (challenge infection)." (PMID 24626328, 2014). "Comparable EPO levels were found in the plasma of control and hemin-preconditioned mice at day 10 post-infection." (PMID 23358441, 2013). "We also observed higher levels of serum erythropoietin in L. donovani infected hamsters compared to control hamsters, which also tended to be higher at 8 weeks post-infection." (PMID 23533629, 2013). "This interesting finding was supported by few studies and was attributed to the increase in RBC counts after infection with hepatitis viruses and also to increased erythropoietin production after hepatic stimulation by chronic infection with hepatitis virus." (PMID 23533739, 2013). "The regression coefficients determined in the structural equation model, and occurrence of low hepcidin levels despite a high incidence of infection, suggested that the down-regulating effect of erythropoietin exceeded the up-regulating effect of inflammation." (PMID 24339866, 2013). "Studies are needed to examine the effects of declining erythropoietin use and hemoglobin levels and increasing intravenous iron use on quality of life, transplantation rates, infection rates and survival." (PMID 24289058, 2013). "The anti-EPO antibody is significantly higher in all four mice strains at infection when compared with the uninfected control (mean OD450nm value = 0.1) (p < 0.0001)." (PMID 23978045, 2013). "There is compelling evidence for a deleterious effect of EPO on the course of infections with intracellular pathogens in mice." (PMID 22094132, 2012). "In general, the bioactivity was greater in cells infected at an MOI of 10 than 1, likely representing a greater concentration of EPO in the supernatant at higher multiplicity of infection." (PMID 23028782, 2012). "In murine CM, exogenous EPO reduces neuronal apoptosis and endogenous, cerebral production of EPO increases during the course of an infection highlighting a neuroprotective role for EPO in CM." (PMID 22741599, 2012).